ERCC4 (ERCC excision repair 4, endonuclease catalytic subunit)
Description:
Catalytic component of a structure-specific DNA repair endonuclease responsible for the 5-prime incision during DNA repair, and which is essential for nucleotide excision repair (NER) and interstrand cross-link (ICL) repair.
Synonyms: ERCC11; XPF; RAD1; FANCQ; XFEPS
Tractability: Small molecule: a high-quality ligand is known; it has a binding pocket of medium quality. PROTAC: UniProt records ubiquitination sites on it; ubiquitination databases record sites on it; its protein half-life has been measured; a small molecule that binds it is known.
Gene: Protein-coding gene on chromosome 16 (13,920,138 to 13,952,348, forward strand). Ensembl gene ENSG00000175595.
Subcellular location: Nucleus; Chromosome
Subcellular location (Human Protein Atlas): Nuclear bodies; Nucleoplasm; Plasma membrane
Pathways (Reactome):
DNA Repair: Dual Incision in GG-NER; Dual incision in TC-NER; Fanconi Anemia Pathway; Formation of Incision Complex in GG-NER; HDR through Single Strand Annealing (SSA)
Gene Ontology:
Molecular function: 3' overhang single-stranded DNA endodeoxyribonuclease activity; damaged DNA binding; DNA binding; DNA endonuclease activity; identical protein binding; protein binding; single-stranded DNA binding; telomerase inhibitor activity; promoter-specific chromatin binding; TFIID-class transcription factor complex binding
Biological process: cellular response to UV; DNA repair; double-strand break repair via homologous recombination; double-strand break repair via nonhomologous end joining; negative regulation of protection from non-homologous end joining at telomere; negative regulation of telomere maintenance; negative regulation of telomere maintenance via telomere lengthening; nucleotide-excision repair; nucleotide-excision repair involved in interstrand cross-link repair; response to UV; telomere maintenance; telomeric DNA-containing double minutes formation; mitotic recombination; resolution of meiotic recombination intermediates
Cellular component: chromosome; chromosome, telomeric region; ERCC4-ERCC1 complex; nuclear body; nucleoplasm; nucleotide-excision repair complex; nucleotide-excision repair factor 1 complex; nucleus
Genetic constraint (gnomAD): Loss-of-function variants: 41 observed, 54.06 expected, observed/expected ratio (o/e) 0.76, 90% interval 0.59 to 0.98. The upper end of that interval is the gene's LOEUF score, 0.98, which puts it in group 4 of 6, group 1 being the genes least tolerant of losing a copy. Missense variants: 1,061 observed, 1,011.3 expected, observed/expected ratio (o/e) 1.05, 90% interval 1 to 1.1. Synonymous variants: 410 observed, 373.77 expected, observed/expected ratio (o/e) 1.1, 90% interval 1.01 to 1.19.
Gene-disease validity (ClinGen):
ClinGen rates the evidence that ERCC4 causes each of these diseases.
xeroderma pigmentosum group F (autosomal recessive): Definitive. Any xeroderma pigmentosum in which the cause of the disease is a mutation in the ERCC4 gene.
Cancer hallmarks: genome instability and mutations (promotes); genome instability and mutations (suppresses)
Homologues: Orthologues: chimpanzee ERCC4 (99% identical), macaque ERCC4 (97% identical), guinea pig ERCC4 (93% identical), dog ERCC4 (92% identical), rabbit ERCC4 (89% identical), pig ERCC4 (89% identical), rat Ercc4 (87% identical), mouse Ercc4 (86% identical), rat Ercc4 (80% identical), tropical clawed frog ercc4 (74% identical), zebrafish ercc4 (62% identical), Drosophila melanogaster mei-9 (41% identical), and 1 more.
Diseases named in the same sentence as ERCC4 in open-access papers:
ERCC4 is named in the same sentence as 111 diseases in open-access papers, as found by Europe PMC text mining. Sharing a sentence is not in itself a finding about the gene and the disease. The quoted sentences say what the papers report.
xeroderma pigmentosum (48 papers, 2010 to 2025). Xeroderma pigmentosum (XP) is a rare genodermatosis characterized by extreme sensitivity to ultraviolet (UV)-induced changes in the skin and eyes, and multiple skin cancers. "According to the protocol for surveillance in ERCC4-associated xeroderma pigmentosum, dermatologic examination and a tone audiogram were performed." (PMID 39652212, 2024). "Usually, ERCC4 mutations are associated with Xeroderma Pigmentosum group F (XP-F) or other Nucleotide Excision Repair Disorders (NERD), like Cockayne syndrome, Fanconi anemia and XFE progeria." (PMID 39652212, 2024). "Genetic alterations in the ERCC4 gene typically cause Xeroderma pigmentosum and other nucleotide excision repair disorders." (PMID 39652212, 2024). "The ERCC4 i.e. excision repair cross-complimentary group 4 gene forms a complex with ERCC1 to encode the two subunits of the ERCC1-XPF (xeroderma pigmentosum complementation group F) nuclease." (PMID 34079756, 2021). "Germline ERCC4 inactivations causes xeroderma pigmentosum complementation group F, Cockayne syndrome, or Fanconi anemia complementation group Q." (PMID 34503238, 2021). "We also observed associations with relevant traits for heterozygous carriers of some rare recessive conditions, e.g., heterozygous carriers of the ERCC4 c.2395C>T (p.Arg799Trp) variant that causes Xeroderma pigmentosum were more susceptible to sunburn." (PMID 30665703, 2019). "In fact, XPF/ERCC4/FANCQ mutations have mainly been identified in patients with Xeroderma pigmentosum (XP) of complementation group F (XP-F), and later in an individual with the XFE progeroid syndrome." (PMID 29325523, 2018). "Pathogenic variants in ERCC4 are associated with disorders such as Xeroderma pigmentosum group F (MIM:278760), Cockayne Syndrome (MIM:216400), a combined form known as XPF/CS (MIM:278760), Fanconi anemia (FANQ) (MIM:615272), and XFE progeroid syndrome (MIM:610965)." (PMID 39769235, 2024). "Variants in the ERCC4 gene have been described to be associated with the following autosomal recessive diseases: xeroderma pigmentosum group F (XPF), xeroderma pigmentosum type F/Cockayne syndrome (XPF/CS), Fanconi anemia complementation group Q (FANCQ), and XFE progeroid syndrome (XFEPS)." (PMID 36816046, 2023). "Apart from the two principal complementation groups of CS (CSA and CSB) with mutations in the ERCC8 and ERCC6 genes, respectively, a small number of CS cases have been reported to carry mutations in the ERCC1 and ERCC4 (xeroderma pigmentosum complementation group F-XPF) genes." (PMID 33920220, 2021). "Thus, one may expect that a deleterious variant in ERCC4 may cause diseases reported in patients with ERCC4 malfunction (i.e., Xeroderma Pigmentosum, Fanconi Anemia Complementation Group F, and Group Q)." (PMID 37124137, 2023). "XPF/ERCC4 mutations are associated with several human diseases: Xeroderma Pigmentosum (XP), Segmental Progeria (XFE), Fanconi Anemia (FA), Cockayne Syndrome (CS), and XP/CS combined disease (XPCSCD)." (PMID 30658521, 2019). "XPF/ERCC4 was originally identified as the defective gene in xeroderma pigmentosum complementation group F (XP-F) since wild type XPF/ERCC4 cDNA complemented human XP-F cells as well as nucleotide-excision repair (NER) deficient Ercc4 and Ercc11 rodent cells." (PMID 30658521, 2019). "g.,ERCC2/XPD,ERCC3/XPB,ERCC4/XPF,ERCC5/XPG,ERCC6/CSB, andERCC8) in the NER pathway frequently cause Xeroderma pigmentosum, trichothiodystrophy, or Cockayne syndrome." (PMID 35593466, 2022). "Previously, ERCC4 gene mutations were identified in Fanconi anemia, skin-photosensitive nucleotide excision repair (NER)-deficient disorder xeroderma pigmentosum, and XFE progeroid syndrome." (PMID 33588785, 2021). "Different cancer syndromes such as a subtype of Xeroderma pigmentosum, XPF, and recently a subtype of Fanconi Anemia, FA-Q, have been attributed to biallelic ERCC4 gene mutations." (PMID 24465539, 2014).
xeroderma pigmentosum (continued). "Biallelic pathogenic variants in one of the seven NER genes coding for the so-called complementation groups, XPA, ERCC3, XPC, ERCC2, DDB2, ERCC4, ERCC5, the NER gene ERCC1, and the gene coding for XP variant, POLH, are the causes of the rare hereditary disease Xeroderma pigmentosum (XP)." (PMID 35174087, 2022). "Together with ERCC4 (xeroderma pigmentosum group F, XPF), ERCC1 forms a structure-specific endonuclease which plays a rate-limiting role in the nucleotide excision (NER) pathway that recognizes and removes DNA adducts that are formed during cisplatin treatment." (PMID 32344513, 2020).
Fanconi anemia (36 papers, 2013 to 2026). Fanconi anemia (FA) is a hereditary DNA repair disorder characterized by progressive pancytopenia with bone marrow failure, variable congenital malformations and predisposition to develop hematological or solid tumors. "XPG-mutant patients display Cockayne syndrome symptoms whereas XPF (ERCC4) mutations yield Fanconi anaemia-like features in addition to common XP manifestation." (PMID 38272916, 2024). "Given its roles in NER, TC-NER, and interstrand crosslink repair, ERCC4 (XPF) is associated with multiple autosomal recessive diseases, including XP, CS, progeroid syndrome, cerebellar ataxia, and Fanconi anemia (FA)." (PMID 34966786, 2021). "In exceptional cases, patients with rare variants in ERCC4/XPF, encoding a subunit of the ERCC1-XPF NER endonuclease, exhibit the combined phenotypes of XP, CS, and Fanconi anemia (FA), a rare inherited bone marrow failure syndrome (IBMFS), designated XPCSFA." (PMID 37364129, 2023). "ERCC4 is an enzyme involved in nucleotide excision-repair DNA damages and is deleted in Fanconi anemia, which is a genomic instability disorder." (PMID 29494553, 2018). "The ERCC4 protein is also required for the repair of DNA interstrand crosslinks and has recently been identified as another component of the Fanconi Anemia pathway and novel Fanconi Anemia protein." (PMID 24465539, 2014). "The carrier of the c.2395C>T mutation in the ERCC4 gene, associated with the development of Fanconi anemia, had no marked clinical manifestations, which is most likely due to the young age of the patient (at the time of examination, she was 5 years old)." (PMID 35052464, 2022). "Moreover, ERCC4 mutations, encoding one of the catalytic subunits of ERCC1-XPF, cause XFE progeroid syndrome and Fanconi anemia, whose patients represent the symptoms of premature aging." (PMID 32526825, 2020). "Rare mutations in ERCC1 and ERCC4/XPF, encoding the NER 5’-endonuclease, may cause complicated features beyond XP, CS, and TTD, including Cerebro-Oculo-Facio-Skeletal Syndrome (COFS), Fanconi anemia (FA), XFE-progeroid syndrome (XFE), XP-CS-FA, and ERCC1-hepatorenal syndrome." (PMID 40924495, 2025). "In addition, the top two enriched KEGG pathways were: 1) the Fanconi Anaemia pathway (represented by ATR, BRIP1, ERCC4, FANCC and POLH) and the FoxO signalling pathway (represented by CREBBP, NLK, PRKAA2, PRKAB1, PTEN and STK11)." (PMID 35768547, 2022).
breast carcinoma (20 papers, 2009 to 2025). "For example, previous researches have displayed significant correlations between single nucleotide polymorphisms in ERCC2, ERCC3, and ERCC4 and the risk of developing lung, skin, and breast cancers." (PMID 39192988, 2024). "There have been numerous studies both domestically and abroad that have confirmed the association between ERCC4 gene polymorphisms and the occurrence of colorectal cancer, gastric cancer, lung cancer, breast cancer, glioma, and osteosarcoma." (PMID 38516408, 2024). "While homozygous R415Q ERCC4 minor alleles (AA) have been associated with increased risk of breast cancer in several studies, carriers of one or two minor alleles were found to have a decreased risk for pancreatic cancer." (PMID 24651674, 2014). "We conclude that the contribution of ERCC4/FANCQ coding mutations to hereditary breast cancer in Central and Eastern Europe is likely to be small." (PMID 24465539, 2014). "In the present study, we investigated the mutational spectrum of the ERCC4/FANCQ coding sequence in a series of German or Byelorussian patients with familial breast cancer." (PMID 24465539, 2014). "This is in agreement with a recent study showing that heterozygous R415Q ERCC4 was associated with benign breast disease, a known breast cancer precursor." (PMID 24651674, 2014). "While this manuscript was under review, an independent study was published that assessed the frequency of ERCC4 mutations in Spanish breast cancer patients." (PMID 24465539, 2014). "More specifically a number of genes in this pathway, such as ERCC4, are tightly associated with breast cancer." (PMID 22346740, 2012). "We previously reported that the minor G allele in a SNP on intron 1 of ERCC4 (rs744154) was associated with protection from breast cancer in the general population (OR under a recessive model 0.61; P=0.0002)." (PMID 19920816, 2009). "On the basis of this finding, we aimed to assess ERCC4-rs744154 as a breast cancer risk modifier in BRCA1 and BRCA2 mutation carriers." (PMID 19920816, 2009). "Breast cancer risk is enhanced by the Rs13181 polymorphism of the ERCC4 gene." (PMID 36157228, 2022). "The other ERCC4 mutation—c.1251T>A—was identified in a bilateral breast cancer case." (PMID 32756499, 2020). "Two ERCC4 loss of function variants have been identified in two breast cancer cases." (PMID 32756499, 2020). "A mutation in the ERCC4 gene can be observed with prostate cancer and breast cancer." (PMID 26547235, 2015). "The rarity of pathogenic mutations in our study seems to be consistent with the view that germ-line mutations in the ERCC4/FANCQ gene might account for only a very small proportion of breast cancer patients in Central and Eastern Europe." (PMID 24465539, 2014). "It is still unclear, however, whether ERCC4 gene alterations also play some role in the inherited component of breast cancer susceptibility." (PMID 24465539, 2014). "Association study of the ERCC4 missense variant p.R415Q in three breast cancer case-control series." (PMID 24465539, 2014). "ERCC4 is therefore a plausible candidate gene to investigate whether inactivating germ-line mutations in its coding sequence may also contribute to breast cancer risk." (PMID 24465539, 2014). "In this study we aimed to evaluate the role of a SNP in intron 1 of the ERCC4 gene (rs744154), previously reported to be associated with a reduced risk of breast cancer in the general population, as a breast cancer risk modifier in BRCA1 and BRCA2 mutation carriers." (PMID 19920816, 2009). "A growing number of genetic evidence indicated that the single-nucleotide polymorphisms (SNPs) in the ERCC4 and ERCC5 genes may vary susceptibility to malignant tumor; previous studies have demonstrated that ERCC4 rs1800067 was associated with the risks of lung cancer, breast cancer, and glioma." (PMID 36033436, 2022).
breast carcinoma (continued). "Germline mutations in DNA mismatch repair genes (BRCA1, BRCA2, CHEK2, ERCC4, FAAP100, and TP53BP1, amongst others) are associated with breast cancer susceptibility." (PMID 27608040, 2016). "We postulate that loss of single-strand DNA repair capacity through XRCC1 deletion in breast cancers creates a dependency on nucleotide excision repair by ERCC4." (PMID 26781748, 2016). "The whole coding region and flanking sequences were analysed by direct sequencing of the 11 exons of the ERCC4 gene in genomic DNA samples from 25 German and 38 Byelorussian breast cancer patients with a family history of disease (Set 1)." (PMID 24465539, 2014). "In the present work, we have sequenced all exons and flanking non-coding sequences of ERCC4 in a total of 75 breast cancer patients." (PMID 24465539, 2014). "Their mutation frequency in cases was not different from controls, suggesting that ERCC4 is not a breast cancer susceptibility gene." (PMID 24465539, 2014). "Genetic alterations of the ERCC4 gene in German and Byelorussian breast cancer patients." (PMID 24465539, 2014). "Because some SNPs in double-strand break repair genes may also impinge on prognosis, we further assessed whether the ERCC4*p.R415Q substitution could affect survival from breast cancer." (PMID 24465539, 2014). "The ERCC4 gene is involved in the nucleotide excision repair (NER) pathway, which has led to the investigation of its role in the susceptibility to develop different types of cancer including breast cancer." (PMID 19920816, 2009).
Cockayne syndrome (14 papers, 2012 to 2024). A multisystem condition characterized by short stature, a characteristic facial appearance, premature aging, photosensitivity, progressive neurological dysfunction, and intellectual deficit. "XPF/ERCC4 mutations can produce Cockayne syndrome (CS), an autosomal recessive disorder associated with a defective TCR." (PMID 30658521, 2019). "Clinical features of XP and Cockayne syndrome (CS) were described in FA due to XPF/ERCC4/FANCQ mutations in another patient (XPCS1CD), and reconciled clinically impaired ICL repair with deficient NER." (PMID 29325523, 2018). "Most of the clinical features observed in our patients, along with the homozygous ERCC4 gene variant, are consistent with Xeroderma Pigmentosum, Type F/Cockayne Syndrome, one of the disorders associated with ERCC4 alterations, although without the typical development of skin cancer." (PMID 39769235, 2024). "In addition, ERCC1 or ERCC4 mutation also have been reported in Cockayne Syndrome." (PMID 34440306, 2021).
colorectal cancer (12 papers, 2012 to 2024). A primary or metastatic malignant neoplasm that affects the colon or rectum. "ERCC4 is linked to the onset or progression of bladder cancer, gastric cancer, oral cancer, and colorectal cancer." (PMID 36157228, 2022). "In this study, we investigate the molecular mechanisms that promote the apoptosis-like event following exposure to B. monnieri extract, using the yeast model for ERCC4 deficient colorectal cancer." (PMID 33668176, 2021). "These bioactive compounds from B. monnieri may have potential as drug candidates for the treatment of ERCC4 deficient colorectal cancer." (PMID 33668176, 2021). "Using multigene panel testing, we found several novel germline mutations that have been rarely reported in hereditary colorectal cancer (e.g., ERCC4, SDHA, and XRCC2), but our limited sample size hindered us from determining their penetrance and relationship with colorectal cancer." (PMID 33194656, 2020). "A difference between normal cells and a subset of colorectal cancers is reduced expression of ERCC4 (excision repair cross-complementation group 4), also called DNA repair endonuclease XPF." (PMID 33668176, 2021). "The aim of the current investigation is to determine the presence, frequency and prognostic impact of ERCC1 or ERCC4 gene copy number alterations in colorectal cancer (CRC)." (PMID 24144331, 2013). "Bacopasaponin C may have potential as a drug candidate for the treatment of colorectal cancer as well as other cancers that show impaired activity or expression of ERCC4 (XPF), the human homologue of RAD1." (PMID 33668176, 2021). "ERCC4 is one of the most significant molecules of Nucleotide Excision Repair (NER), which has been researched due to its high expression in colorectal cancer (CRC)." (PMID 34993023, 2021). "Despite previous studies on the relationship between inflammation and tumors receiving significant attention from researchers worldwide, the mechanism by which ERCC4 influences the occurrence and development of IBD and subsequently leads to colorectal cancer at the protein level remains unclear." (PMID 38516408, 2024).